TAF4B (TATA-box binding protein associated factor 4b)
Description:
Cell type-specific subunit of the general transcription factor TFIID that may function as a gene-selective coactivator in certain cells. TFIID is a multimeric protein complex that plays a central role in mediating promoter responses to various activators and repressors. TAF4B is a transcriptional coactivator of the p65/RELA NF-kappa-B subunit. Involved in the activation of a subset of antiapoptotic genes including TNFAIP3. May be involved in regulating folliculogenesis. Through interaction with OCBA/POU2AF1, acts as a coactivator of B-cell-specific transcription. Plays a role in spermiogenesis and oogenesis.
Synonyms: TAFII105; TAF2C2; SPGF13
Tractability: PROTAC: ubiquitination databases record sites on it.
Gene: Protein-coding gene on chromosome 18 (26,226,393 to 26,391,685, forward strand). Ensembl gene ENSG00000141384.
Subcellular location: Nucleus; Cytoplasm
Subcellular location (Human Protein Atlas): Nucleoplasm; Nucleoli fibrillar center
Pathways (Reactome):
Gene expression (Transcription): RNA Polymerase II Pre-transcription Events; RNA Polymerase II Promoter Escape; RNA Polymerase II Transcription Initiation; RNA Polymerase II Transcription Initiation And Promoter Clearance; RNA Polymerase II Transcription Pre-Initiation And Promoter Opening
Disease: HIV Transcription Initiation; RNA Polymerase II HIV Promoter Escape; Transcription of the HIV genome
Gene Ontology:
Molecular function: DNA binding; NF-kappaB binding; RNA polymerase II general transcription initiation factor activity; protein heterodimerization activity; RNA polymerase II-specific DNA-binding transcription factor binding
Biological process: mRNA transcription by RNA polymerase II; positive regulation of transcription initiation by RNA polymerase II; transcription initiation at RNA polymerase II promoter; DNA-templated transcription; DNA-templated transcription initiation
Cellular component: cytoplasm; fibrillar center; nucleoplasm; nucleus; transcription factor TFIID complex
Genetic constraint (gnomAD): Loss-of-function variants: 34 observed, 70.03 expected, observed/expected ratio (o/e) 0.49, 90% interval 0.37 to 0.65. The upper end of that interval is the gene's LOEUF score, 0.65, which puts it in group 2 of 6, group 1 being the genes least tolerant of losing a copy. Missense variants: 900 observed, 941.95 expected, observed/expected ratio (o/e) 0.96, 90% interval 0.9 to 1.01. Synonymous variants: 355 observed, 368.16 expected, observed/expected ratio (o/e) 0.96, 90% interval 0.88 to 1.05.
Homologues: Orthologues: chimpanzee TAF4B (99% identical), macaque TAF4B (97% identical), pig TAF4B (89% identical), dog TAF4B (88% identical), rabbit TAF4B (87% identical), guinea pig TAF4B (80% identical), mouse Taf4b (79% identical), rat Taf4b (72% identical), tropical clawed frog TAF4B (42% identical), zebrafish taf4b (32% identical), Caenorhabditis elegans taf-4 (15% identical). Paralogues in human: TAF4 (37% identical).
Diseases named in the same sentence as TAF4B in open-access papers:
TAF4B is named in the same sentence as 19 diseases in open-access papers, as found by Europe PMC text mining. Sharing a sentence is not in itself a finding about the gene and the disease. The quoted sentences say what the papers report.
Azoospermia (4 papers, 2020 to 2025). Absence of any measurable level of sperm,whereby spermatozoa cannot be observed even after centrifugation of the semen pellet. "Finally, a heterozygous TAF4b mutation is predicted in the genome of the mother of three infertile brothers that display homozygous and truncating mutations in TAF4b causing their non-obstructive azoospermia." (PMID 39829852, 2025). "In addition to studies of TAF4b in mice, human males who express a truncated version of the TAF4b protein are infertile owing to progressive azoospermia, and single nucleotide polymorphisms in human TAF4b have been linked to nonobstructive azoospermia." (PMID 37900284, 2023). "While Nanos2 prevents differentiation, the TATA-box Binding Protein Associated Factor-4b (TAF4B) controls the expression of genes promoting differentiation and self-renewal of SSCs, and TAF4B deletion results in nonobstructive azoospermia (NOA) or oligozoospermia in mice and men." (PMID 38764035, 2024).
infertile (4 papers, 2020 to 2025). "Since human studies implicate TAF4B as important for fertility and oocyte quality, our efforts to understand the molecular mechanisms underlying the expression and function of TAF4b in mouse germ cell development may contribute to our increased understanding of human fertility and infertility." (PMID 31914128, 2020). "In addition, it has recently been reported that disruption of TAF4b and ZFP628 by crisper-cas9 induces infertility in male mice." (PMID 34556135, 2021).
Bladder Cancer (2 papers, 2021 to 2024). "Employing the Xiantao platform (xiantaozi.com), our observations revealed that TAF4B expression was generally subdued across a spectrum of cancer tissues, including BCa, and displayed variability in expression levels correlating with different stages and subtypes of bladder cancer." (PMID 39430741, 2024).
granulosa cell tumor (1 paper, 2014). A slow-growing, malignant tumor, characterize by the presence of granulosa-like cells and Call-Exner bodies, that is almost always found in the ovary. "Here, we show that TAF4B mRNA correlates with Cyclin D2 mRNA expression in human granulosa cell tumors." (PMID 24653979, 2014).
male infertility (1 paper, 2010). The inability of the male to effect fertilization of an ovum after a specified period of unprotected intercourse. "Similarly, inactivation of Taf4b results in severe germ cell depletion characterized by tubules of only Sertoli cells and male infertility." (PMID 21179456, 2010).
ovarian carcinoma (1 paper, 2014). A malignant neoplasm originating from the surface ovarian epithelium. "Other genes linked to ovarian cancer were also identified as TAF4B targets in TAF4B-overexpressing SIGCs, including c-Jun, matrix metalloproteinase-3 (Mmp-3), and Fibronectin-1 (Fn1)." (PMID 24653979, 2014). "TAF4B is relevant to the discussion of TAFs in ovarian cancer because its expression is enriched in the ovary compared to other tissues, and it is required for proper ovarian follicle development and murine fertility." (PMID 24653979, 2014). "TAF4B is not as frequently altered in ovarian cancer, but nonetheless exhibits amplifications, copy number gains, or mRNA upregulation in 25% of HGSC." (PMID 24653979, 2014).
ovarian tumor (1 paper, 2014). "While this mechanism has not been investigated in the ovary, it could represent another way that TAF4B contributes to regulation of the immune microenvironment and protection from apoptosis, particularly in ovarian tumors with constitutively activated NFκB signaling." (PMID 24653979, 2014). "For the sake of this discussion, we will focus on TAF2, TAF4, TAF4B, and TAF9 as illustrative examples of how specific TAF subunits may be involved in regulating ovarian tumor properties." (PMID 24653979, 2014).
premature ovarian failure (1 paper, 2016). "Taf4b-deficient female mice suffer from hallmarks of primary ovarian insufficiency (POI) including persistent estrous, elevated serum follicle stimulating hormone (FSH) and accelerated primordial follicle depletion." (PMID 27341508, 2016).
sterility (1 paper, 2016). "Deletion of TAF4b in both female and male gonads results in sterility." (PMID 27304889, 2016).
teratoma (1 paper, 2023). A non-seminomatous germ cell tumor characterized by the presence of various tissues which correspond to the different germinal layers (endoderm, mesoderm, and ectoderm). "While Taf4b-deficient testes display similar kinetics in male germ cell loss and fertility disruption, our Taf4b-deficiency presented here is on a C57Bl/6 background where we might not expect to see these teratomas." (PMID 37900284, 2023).
Turner syndrome (1 paper, 2025). Turner syndrome is a chromosomal disorder associated with the complete or partial absence of an X chromosome. "Furthermore, TAF4b-dependent molecular events significantly overlap with those disrupted in Turner syndrome and Fragile X-associated POI (FX-POI), two prominent genetic examples of POI." (PMID 39829852, 2025). "In addition, we observed reduced expression of X chromosome genes and that Taf4b−/− oocytes share significant transcriptome similarities with fetal oocytes collected from a mouse model of Turner Syndrome." (PMID 39829852, 2025).
cardiovascular disease (1 paper, 2023). "In addition, we identified several interesting candidates such as Taf4b, Tmc8, Wdr11, and Grk5 that were previously associated with different chronic metabolic and inflammatory diseases including T2D, cardiovascular disease, and/or IBD69,70,74,76,77,80,81." (PMID 36788222, 2023).
tumor (1 paper, 2014). "TAF4B may also contribute to regulation of tumor microenvironment due to its estrogen-responsiveness and ability to act as a cofactor for NFκB." (PMID 24653979, 2014). "While TAF4B could potentially be involved in mediating anti-apoptotic effects, TAF9 is illustrative of a TAF acting as a putative tumor suppressor, since it is downregulated or deleted in 98% of HGSC." (PMID 24653979, 2014). "It is not clear, however, whether the upregulation of TAF4B in these tumors occurs in the OSE-derived cells (suggesting cell-autonomous effects) or in the tumor stroma (suggesting microenvironment effects)." (PMID 24653979, 2014).
TAF4B also shares sentences with these, for which no sentence is quoted: cancer (2 papers); colon cancer (1); cyst (1); glioblastoma (1); promyelocytic leukemia (1); serous ovarian tumors (1).